ALB (albumin)
Diseases named in the same sentence as ALB in open-access papers (continued):
Sharing a sentence is not in itself a finding about the gene and the disease.
kidney damage (continued). "Treatment with MCC950 (10 mg/kg), US + MCC950 (5 mg/kg), and US + MBs + MCC950 (5 mg/kg) significantly reduced serum creatinine, blood urea nitrogen, and albumin-to-creatinine ratios, and alleviated kidney damage and fibrosis compared to untreated CKD rats." (PMID 40822454, 2025). "Multiple regression analysis revealed that sex, age, nephropathy, peripheral neuropathy, hemoglobin, serum albumin, and low-density lipoprotein cholesterol levels were significant explanatory variables for PhA." (PMID 40786473, 2025). "Twenty-four–hour urinary albumin excretion, a marker of kidney damage, was up to 1,000-fold increased in Alport mice, and NR treatment prevented this increase in both sexes." (PMID 40059824, 2025). "Metformin lowered BUN, urea, and creatinine; increased body weight and albumin; and reversed histopathological kidney damage." (PMID 41471323, 2025). "In fact, small amounts of albumin can also be due to stress and diet; however, increased levels of albumin indicate kidney damage." (PMID 39819647, 2025). "Kidney damage and impaired function can be confirmed by presence of albumin in the urine (albumin to creatinine ratio above 30 mg/g) and/or an estimated glomerular filtration rate (GFR) of less than 60 mL/min/1.73 m2, respectively." (PMID 40352145, 2025). "The potential of PLISA was tested by the detection of humanserum albumin (HSA), a biomarker of kidney damage when found in urine,and prostate-specific antigen (PSA), a key serum biomarker of prostatecancer." (PMID 40556296, 2025). "On the other hand, patients with nephropathy due to other causes have a significant positive correlation between T lymphocytes and CD4+ T cells with serum albumin concentration." (PMID 40277801, 2025). "The ratio of urine albumin (mcg/L) to creatinine (mg/L), uACR, is clinically used to determine kidney damage in humans, with the normal range being less than 30 mg/g." (PMID 39765751, 2024). "Monitoring urine albumin-to-creatinine ratio (uACR) has become the gold standard for nephropathy diagnosis and control." (PMID 39202190, 2024). "Given the relative inconvenience of clinical urinary albumin testing, utilizing lipid levels as a significant biomarker for early kidney damage offers a more convenient method to evaluate patients’ health status." (PMID 39491271, 2024). "This means that both the structural integrity and the amount of albumin are affected by the severity of kidney damage." (PMID 38542146, 2024). "Elevated albumin/creatinine ratios (ACR) in urine samples provided an estimate on the extent of kidney damage occurring in response to treatments." (PMID 39310112, 2024). "This group displayed a consistent trend toward more pronounced renal impairment, as reflected by higher serum creatinine levels, lower eGFR, and elevated urine albumin-to-creatinine ratios, indicative of early nephropathy." (PMID 39445045, 2024). "A review study noted that albumin, a pro-inflammatory and pro-fibrotic protein, present in the glomerular filtrate indicates kidney damage." (PMID 39445274, 2024). "Hg, Cd, and Pb ions in the blood bind to thiol-containing biomolecules such as albumin, glutathione, and cysteine to some extent, leading to kidney damage." (PMID 39104895, 2024). "Nephropathy occurs when the uACR is >30 mg/g creatinine or microalbuminuria is present (urinary albumin 30–300 mg/24 h)." (PMID 39202190, 2024). "Frequencies of subjects having diabetic neuropathy, retinopathy, and nephropathy (urinary albumin ≥ 30 mg/gCr) were 42.1%, 36.8%, and 52.6%, respectively." (PMID 38223524, 2024). "In a follow-up therapy study using the same albumin binder-carrying compound, it was shown that nephropathy occurred for different doses tested, although to a lesser extent than the compound without the albumin binder." (PMID 38399470, 2024).
kidney damage (continued). "Nephropathy was assessed using the albumin-to-creatinine ratio, and the glomerular filtration rate (GFR) was calculated using the Modification of Diet in Renal Disease (MDRD) formula." (PMID 39553031, 2024). "In patients with nephropathy, the spot urine albumin/creatinine ratio, the spot urine protein/creatinine ratio, and 24-h urine albuminuria and proteinuria should be monitored." (PMID 37370958, 2023). "In a study by Al Shammari on male rats with induced kidney damage, ginger supplementation significantly elevated serum albumin and protein." (PMID 37228303, 2023). "Albumin is produced in the liver, and its decrease indicates liver damage, which is a direct indicator of the degree of liver and kidney damage." (PMID 37965553, 2023). "The CRP/albumin (CAR) ratio has also been associated with inflammation and nephropathy in diabetic patients." (PMID 37370958, 2023). "After treatment with ACT001 or PPC, urinary microalbumin decreased, and mice treated with PPC showed a more highly significant decrease.The albumin-to-creatinine ratio in the urine (ACR) is an important indicator in early kidney damage." (PMID 37978497, 2023). "Albumin/creatinine ratio in urine should be checked as well as proteinuria and glomerular filtration rate to diagnose kidney damage." (PMID 37124176, 2023). "Functionally, there was initial glomerular hyperfiltration and increased albumin excretion; as nephropathy progresses, there is an increase in proteinuria and a decrease in GFR." (PMID 37990213, 2023). "Since high urinary albumin levels are a typical marker of nephropathy, we performed histological and biochemical analysis on the kidneys." (PMID 36787192, 2023). "Brensocatib treatment also entailed a significant reduction in the urine albumin-to-creatinine ratio, indicating decreased kidney damage, as well as a significant reduction in blood urea nitrogen level, suggesting improved renal function." (PMID 37441081, 2023). "Fourth, this study excluded people with positive urinary albumin, thereby preventing us from understanding the effect of proteinuria on kidney damage." (PMID 36871015, 2023). "Studies have shown that the PRR can regulate the RAS when it is induced by angiotensin II (Ang II) or DOCA-salt (deoxycorticosterone acetate), Adriamycin, or albumin overload-induced nephropathy." (PMID 37049779, 2023). "A recent study also showed that the PRR is a critical factor in regulating intrarenal RAS activation during albumin overload-induced nephropathy." (PMID 37049779, 2023). "It has been found in human nephropathy models that IgG levels are positively correlated with serum albumin and serum IgA levels and negatively correlated with serum cholesterol levels in patients with immunoglobulin A nephropathy (IgAN)." (PMID 36766355, 2023). "The AMPK signaling pathway improves DN by reducing uric acid, serum albumin, creatinine, and kidney damage." (PMID 36094934, 2022). "Nephropathy was confirmed by urine albumin/creatinine ratio and estimated glomerular filtration rate; retinopathy was diagnosed using fundus photograph." (PMID 35209907, 2022). "Proteinuria, urine P-CAST, urea nitrogen, creatinine, IgG, albumin, total protein, and SLEDAI-2K are associated with kidney damage." (PMID 35883502, 2022). "We found that Sirt7 deficiency attenuated AKI, which was evidenced by lower urinary excretion of both albumin and biomarkers of kidney damage, such as Hsp72, KIM-1, and SerpinaA3." (PMID 35269715, 2022). "age >18 years; type 1 DM; glycated hemoglobin (HbA1C) 6% to 10%; nephropathy (defined as urinary albumin to creatinine ratio of >2.1 mg/mmol in men and >2.8 mg/mmol in women); and estimated GFR ≥ 80 mL/min." (PMID 36060954, 2022). "The main predictor of early kidney damage is thought to be urine albumin and NAG, the most active lysosomal glycosidase." (PMID 36557204, 2022).
kidney damage (continued). "The decrease in albumin and an increase in globulins, the decrease in the A: G ratio is indicative of inflammation, aspergillosis, nephropathies, and liver failure." (PMID 36503512, 2022). "Among these, NAG, NGAL, albumin, and transferrin showed the greatest significance, suggesting that these biomarkers are more sensitive for diagnosing kidney damage due to tobacco use." (PMID 35887529, 2022). "Elevated proteinuria and P-CAST and decreased serum albumin and IgG are common markers of kidney damage." (PMID 35883502, 2022). "The Nephropathy Prescription I can alleviate albuminuria, increase serum albumin levels, lower blood lipid levels, and reduce the fusion of foot processes of podocytes in mice with adriamycin-induced nephropathy." (PMID 38149181, 2022). "Atorvastatin accelerated kidney damage, as presented by the increase in proteinuria levels and significant decrease in serum ALB levels." (PMID 36471414, 2022). "Nephropathy Prescription I alone or combined with hormone and immunosuppressive agents can reduce the resolution of edema, increase serum albumin, reduce blood lipids, and reduce hormonal side effects." (PMID 38149181, 2022). "A meta-analysis of randomized controlled trials published in 2015 demonstrated a 32.1% reduction in urinary albumin excretion following an average reduction in sodium intake of 2.1 g, more so in patients with kidney damage." (PMID 36143852, 2022). "Diagnosis of CKD is based on a persistent reduction of eGFR and/or markers of kidney damage, including high urine albumin-creatinine ratio (UACR) or urine protein-creatinine ratio (UPCR)." (PMID 36140563, 2022). "Kidney damage often manifests as proteinuria and hypoproteinaemia, which reduce ALB and result in low ALI." (PMID 36425070, 2022). "The ACR test detects abnormalities through albumin reading in an early sign of kidney damage, and the GFR determines the stages of kidney disease." (PMID 35383215, 2022). "Diabetic mice displayed increased urine albumin to creatinine ratios (uACR), an indicator of kidney damage which was assessed at 12 weeks after diabetic establishment." (PMID 35342338, 2022). "Prevalence of impaired kidney function (eGFR < 60 ml/min; 14.9% vs. 18.4%, p = 0.580) as well as nephropathy (albumin/g creatinine > 20 mg/g; 43.2% vs. 45.4%, p = 0.777) was comparable between CSII and ICT." (PMID 34301317, 2021). "We also found that patients in this group had a higher rate of nephropathy defined by albumin/creatinine ratio." (PMID 34537062, 2021). "In this model, CSL040 at 20 and 60 mg/kg significantly attenuated kidney damage at 24 h, with significant reductions in cellular infiltrates and urine albumin, consistent with protection from kidney damage." (PMID 33334893, 2021). "Microalbuminuria occurs during the early stages of DN and a urine albumin to creatine ratio (UACR) of 30–299 mg/gCr is indicative of early-stage nephropathy." (PMID 32974732, 2021). "Several predictors were consistent with the latest medical research: fibrinogen, plasma albumin, hematocrit for nephropathy, and adenosine deaminase-2 for retinopathy." (PMID 34098959, 2021). "The excessive presence of albumin in urine is considered an indicator of kidney damage, since it represents alterations in both filtration and reabsorption processes." (PMID 33800425, 2021). "Kidney damage was assessed by albuminuria (albumin-to-creatinine ratio, ACR) and classified as mild, moderate, or severe (ACR1: <300, ACR2: 300–3000, and ACR3: 3000 mg/g)." (PMID 33575899, 2021). "Clinical studies reported that angiotensin-converting enzyme inhibitors (ACE-I) and angiotensin II receptor blockers (ARBs) inhibit increases in urine albumin/urine protein and progression of renal dysfunction in early-stage nephropathy." (PMID 32974732, 2021). "In mice, glutamate inhibits the fusion of podocytes with ADR, nephropathy, cell apoptosis, renin expression and reduces urine albumin." (PMID 34938183, 2021).
kidney damage (continued). "Subjects underwent a detailed standard evaluation to detect diabetic retinopathy (fundus photography) and nephropathy (defined as urinary albumin excretion ≥ 30 mg/24 h)." (PMID 33532603, 2021). "The frequencies of diabetic neuropathy, retinopathy, and nephropathy (urinary albumin ≥ 30 mg/gCr) were 59.5%, 35.1%, and 54.1%, respectively." (PMID 34484124, 2021). "The increased excretion of albumin (or total protein) with urine is a well-recognized marker of kidney damage." (PMID 34439968, 2021). "CKD was defined as the presence of kidney damage (urine albumin-creatinine ratio ≥30 mg/g) or estimated glomerular filtration rate (eGFR) < 60 mL/min/1.73 m2." (PMID 34869437, 2021). "Among these biochemical markers of kidney damage are serum creatine kinase (sCK), serum creatinine (sCr), serum blood ureic nitrogen (sBUN), serum albumin (ALB), and recently through Cystatin-C (Cyst-C)." (PMID 34639516, 2021). "Four studies were evaluated which considered the onset of nephropathy, the data showing that the HbA1c cutoff of 6.5% (48 mmol/mol) was appropriate with a significant increase in the urine albumin/creatinine ratio." (PMID 33141338, 2021). "Albuminuria, a marker of kidney damage, is the consequence of albumin leakage across the glomerular podocyte filtration barrier into the urine and the increased excretion of urinary albumin." (PMID 33129312, 2020). "Microalbuminuria is an early predictor and a sensitive assay to detect urinary albumin excretion which can precede the development of overt nephropathy in T2DM." (PMID 33520516, 2020). "Podocytes, responsive cells that block blood albumin leakage into urine, are severely damaged by the toxin used to induce kidney damage in this model, making it difficult to demonstrate the reduction of uAlb with drug treatment." (PMID 32324796, 2020). "in 2013 designed an aptamer against albumin-AGE for therapeutic purposes and showed that aptamer administration decreases the albumin-AGE toxicity thereafter nephropathy in diabetic mice." (PMID 32612182, 2020). "The ideal state would be that all biochemistry laboratories measure both creatinine as the marker of kidney function and urinary albumin as the marker of kidney damage." (PMID 31379462, 2019). "It is, therefore, possible that the moderate consumption of walnuts can reduce kidney damage and inflammation and improve endothelial function, and thereby reduce urinary albumin excretion in patients with CKD." (PMID 31881702, 2019). "In clinical practice, kidney damage is generally detected by changes in serum creatinine and a creatinine-based estimate of the glomerular filtration rate (eGFR), and/or urinary albumin/protein excretion." (PMID 31877774, 2019). "The prevalence of diseases and cardiac events was higher in the ESTHER study, while elevated urinary albumin levels (≥ 20 mg/L) were more prevalent in the UK Biobank indicating a higher proportion of participants with potential kidney damage in this cohort." (PMID 31375970, 2019). "Spironolacton decreased the urinary albumin excretion, lipids and fasting glucose levels, and alleviated kidney damage." (PMID 30734886, 2019). "Participants were diagnosed with nephropathy by having an elevated urine albumin-to-creatinine ratio (ACR) > 30 mg/g." (PMID 31772941, 2019). "We measure the levels of albumin in urine as to assess for kidney damage, and compare the correlations of the concentrations of the endogenous serum indicators, creatinine and cystatin C, with changes in renal function." (PMID 29394255, 2018). "We aimed to identify urinary biomarkers to early diagnosis nephropathy before identifiable alternations in kidney function or urine albumin excretion occurs." (PMID 30486327, 2018). "Due to the pathophysiological importance of hyperfiltration in long-term kidney damage, the Study Group suggests avoiding, whenever possible, treatments which potentially increase hyperfiltration, such as albumin infusion." (PMID 29949013, 2018).
kidney damage (continued). "In this study, we found a significantly increased urine albumin/creatinine ratio, indicating the presence of nephropathy in patients with epilepsy who received long-term AED therapy." (PMID 29593629, 2018). "Diabetic retinopathy/nephropathy (urine albumin-to-creatinine ratio ≥ 30 mg/g) was observed in 13.7%/19.1%, 13.9%/19.7%, 20.2/29.7%, and 19.5/24.7% of the young-male, young-female, old-male, and old-female diabetics, respectively." (PMID 28196151, 2017). "Increased serum levels of creatinine and phosphorus, and decreased serum levels of albumin are the first markers of kidney damage due to high glucose concentrations." (PMID 28774305, 2017). "The PREVEND trial found a correlation between urine albumin excretion, a marker of kidney damage, and cigarette smoking." (PMID 28306749, 2017). "An increased level of urinary albumin excretion is an early sign of kidney damage and persistent albuminuria, typically ACR ≥ 30 mg/g lasting for more than three months, has been included as a diagnostic standard for CKD." (PMID 28592243, 2017). "A total of 929 Nevisians underwent urine testing, and 126 individuals (13.5%) had a urine albumin level of at least 30 mg/dL, which is suggestive of kidney damage." (PMID 28056873, 2017). "RGZ also provided a protective effect from kidney damage as shown by the normalization of plasma creatinine and albumin levels compared with control values." (PMID 28101123, 2017). "Microalbuminuria and increased urine albumin to creatinine ratio are regarded as early predictors of kidney damage." (PMID 26871707, 2016). "Nephropathy was defined as a urinary albumin-to-creatinine ratio > 30 mg/g creatinine, above the micro albuminuria level." (PMID 26834530, 2016). "Overt kidney damage and filtration impairment can be manifested at percent change by elevated blood creatinine levels and albumin leakage." (PMID 27649140, 2016). "Screening for nephropathy is done by measuring the amount of albumin in the urine and estimating the glomerular filtration rate." (PMID 27546934, 2016). "The biochemical results showed that the Dox group developed kidney damage, as evidenced by albuminuria and increased urine albumin/creatinine ratio (p < 0.05) at every time-point (Days 7 to 28)." (PMID 26063968, 2015). "As in vivo functional evidence of kidney damage, we also determined albumin/creatinine ratios in urine samples obtained at GD6/GD7, GD13, GD18 and PPD8." (PMID 25860260, 2015). "Screening for kidney damage identified 19 adults (14.0 %) with an excess of RBP (8.1 %) or albumin (10.3 %) among the 136 adults with an excessive cadmium body burden." (PMID 25971522, 2015). "In the present study, both VPA and Dex treatments administered, prior to IR injury significantly reduced the urine albumin level and kidney histopathologic score (reduced kidney damage) at 3 h post-IR." (PMID 25970334, 2015). "The first sign of nephropathy was detected by microalbuminuria (presence of albumin in urine) but doesn't cover all patients with renal impairment." (PMID 24876663, 2014). "For functional evidence of kidney damage, we also determined albumin/creatinine ratios in urine samples obtained serially during pregnancy." (PMID 25393290, 2014). "Among the clinical signs of nephropathy, the appearance of low but abnormal levels (>30 mg/day) of albumin in the urine, known as MAU, is first to occur." (PMID 25120629, 2014). "Hyperglycemia leads to nephropathy by various mechanisms, such as increased endothelial cell permeability to albumin, hypertrophy and thickening of the basement membrane." (PMID 23646149, 2013). "CKD is diagnosed through GFR measurement and the presence of kidney damage identified by abnormalities in the composition of markers, such as albumin in urine, and pathological abnormalities in imaging tests." (PMID 23536858, 2013). "FVC (% predicted P<0.001), and FEV1 (% predicted P<0.05) were lower in diabetic people with nephropathy compared to those with normal renal albumin excretion." (PMID 23618325, 2013).